GGT1 (gamma-glutamyltransferase 1)
Diseases named in the same sentence as GGT1 in open-access papers (continued):
Sharing a sentence is not in itself a finding about the gene and the disease.
infection (3 papers, 2017 to 2024). The state of being infected such as from the introduction of a foreign agent such as serum, vaccine, antigenic substance or organism. "Because Acivicin is not a selective GGT1 inhibitor, we next determined if knockdown of GGT1 expression in LET1 cells would also reduce their susceptibility to infection." (PMID 28085958, 2017). "Consistent with this resistance mechanism, inhibition of the cysLT pathway enzymes, in particular GGT1 reduced the susceptibility of T1AECs in CBFβΔLysM mice to infection, as did antagonism of the cysLT receptor CysLT1." (PMID 28085958, 2017). "The transcription level of most genes involved in GSH metabolism, including Gpx1, Ggt1, Gsr, Pgd, Anpep and Lap3, was significantly higher post-infection than pre-infection in the delta group but not in the omicron group." (PMID 39759510, 2024).
kidney disease (2 papers, 2019 to 2021). "Seven of those renal disease-related proteins had higher weighted scores (> 0.60), including Ggt1 (0.941), Camp (0.906), Cdh1 (0.835), Lpo (0.833), Scpep1 (0.803), Anpep (0.644), and Ptgds (0.603)." (PMID 33981220, 2021). "Notably, among these abnormally expressed proteins, 19 proteins were reported as kidney disease markers (Ada, Ambp, Anxa1, B2m, Camp, Col1a1, Cp, Ggt1, Glb1, Lgfbp7, Lifr, Lpl, Plau, Ptgds, S100a8, Serpinc1, Serpina3k, Tff1, and Vtn) (highlight in green)." (PMID 31708494, 2019).
aorta (1 paper, 2014). "Meanwhile, the expressions of GGT-1, ICAM-1 and VCAM-1 were significantly decreased in the whole aorta plaques." (PMID 25326709, 2014).
GGT1 also shares sentences with these, for which no sentence is quoted: benign prostatic hyperplasia (5 papers); acute pancreatitis (2); Alzheimer disease (2); lung adenocarcinoma (2); Obesity (2); Parkinson disease (2); renal cell carcinoma (2); adenocarcinoma (1); alcoholic hepatitis (1); benign prostate tumors (1); breast tumors (1); calculus (1); colorectal cancer (1); COVID-19 (1); Cowden disease (1); cyst (1); dementia (1); dermatitis (1); gastric cancer (1); goiter (1); Graves disease (1); heart failure (1); Hepatic steatosis (1); Huntington disease (1); Infertility (1); intraductal papillary mucinous neoplasm (1); liver cancer (1); neurodegenerative disease (1); papillary carcinoma (1); thyroid cancer (1).
A further 2 diseases each share a sentence with GGT1 in 1 paper.